GPHN (gephyrin)
Diseases named in the same sentence as GPHN in open-access papers (continued):
Sharing a sentence is not in itself a finding about the gene and the disease.
Anxiety (continued). "In addition, DHM restores gephyrin expression, improves inhibitory synaptic transmission efficiency, and reverses GABAA receptor dysfunction in AD-related anxiety." (PMID 40740995, 2025). "In addition, DHM reduces anxiety-like behavior in mice by repairing GABAA receptors and synaptic function impaired by social isolation, restoring ATP levels and gephyrin expression." (PMID 40740995, 2025). "The lack of gephyrin palmitoylation reduces the GABAAR function of the basolateral amygdala and causes anxiety." (PMID 36438847, 2022). "Consistent with this, deletion of gephyrin selectively in forebrain mouse neurons markedly reduces GABAAR-positive puncta in the hippocampus and cortex, together with increased anxiety-like behavior and increased lethality presumably owing to prevalent epileptic seizures." (PMID 33532714, 2021). "While it was originally proposed that IgSF9b links to Nlgn2 via S-SCAM as a bridging molecule and thereby recruits gephyrin and other GABAergic synapse components, we subsequently found that, at least within the amygdala anxiety circuitry, IgSF9b and Nlgn2 do not appear to act at the same synapses." (PMID 41105221, 2025). "In contrast, overexpression of nNOS in the BLA exacerbated anxiety‐like behaviors by reducing the surface expression of GABAAR and abolished the anxiolytic effect of physical exercise, indicating that physical exercise exerts anxiolytic effects through nNOS‐mediated gephyrin S‐nitrosylation." (PMID 38965798, 2024). "In contrast, mice with DHM treatment, while demonstrating higher levels of ATP and a significant reduction in anxiety-like behavior, showed a higher expression of gephyrin protein in the hippocampus, suggesting that DHM restores ATP levels and maintains the expression of gephyrin in isolated mice." (PMID 32742262, 2020). "In addition, high anxiety is accompanied by inhibited gephyrin palmitoylation and suppressed synaptic function of GABAAR in the basolateral amygdala of rats, while diazepam mediates the anxiolytic effect through activating DHHC12 and increasing gephyrin palmitoylation." (PMID 34803494, 2021). "No amelioration of the Nlgn2 KO anxiety phenotype was observed in male or female Nlgn2 KO/MDGA2 Het mice, consistent with the lack of an effect of MDGA2 Het on gephyrin aggregation and GABAergic synaptic transmission." (PMID 39284869, 2024).
schizophrenia (14 papers, 2012 to 2024). A major psychotic disorder characterized by abnormalities in the perception or expression of reality. "Partial genomic gephyrin deletions are associated with ASDs and schizophrenia, indicating pathological links to gephyrin disruption." (PMID 38503929, 2024). "Furthermore, a recent study showed that enrichment of copy-number variations in GABAergic genes from individuals with schizophrenia that were identified duplications and deletions in the region of GPHN." (PMID 36386965, 2022). "Furthermore, we demonstrate that aberrant GPHN splicing, reported in neuropsychiatric pathologies (schizophrenia, Autism Spectrum Disorders (ASDs), and epileptogenesis), are encompassed in a myriad of alternative transcripts that are expressed at low levels in brain of healthy individuals." (PMID 35717442, 2022).
hyperekplexia (8 papers, 2012 to 2024). "Mutations in GPHN and GLRA1 (Glycine receptor alpha 1) have been linked to hyperekplexia in humans, a disorder that manifests from childhood and is characterized by exaggerated startle responses, stiffness, and an inability to move." (PMID 39068495, 2024). "Although dysfunction of gephyrin probably also affects GlyR clustering, this seems to have no significant clinical consequences as the typical symptom of glycinergic defects, hyperekplexia, is missing as already observed in patients with heterozygous GPHN deletions." (PMID 26613940, 2015). "In addition to mutations in the genes GLRB (encodes glycine receptor β-subunit), SLC6A5 (encodes glycine transporter 2) and GPHN (encodes the integral membrane protein gephyrin), mutations in the gene GLRA1 (encodes the α1-subunit of the GlyR) account for 40 - 80% of hyperekplexia." (PMID 23006332, 2012).
Alzheimer disease (5 papers, 2016 to 2022). A progressive, neurodegenerative disease characterized by loss of function and death of nerve cells in several areas of the brain leading to loss of cognitive function such as memory and language. "In addition, the diagnosis of Alzheimer’s disease is associated with an abnormal clustering of gephyrin and its lowering correlates with an increasing severity." (PMID 32977518, 2020). "Since gephyrin is involved in synaptic organization, the authors concluded that synaptic dysfunction is an early event in Alzheimer’s disease." (PMID 35053014, 2021). "In the brain tissue of patients with Alzheimer’s disease, an accumulation of gephyrin in co-localization with β-amyloid plaques was detected." (PMID 35053014, 2021).
stiff-man syndrome (5 papers, 2012 to 2022). "Subsequently, autoantibodies against synaptic proteins were described, first against amphiphysin in “three women with the stiff-man syndrome and breast cancer” and then against gephyrin in one SMS patient." (PMID 35084720, 2022).
Epileptic encephalopathy (4 papers, 2015 to 2025). A condition in which epileptiform abnormalities are believed to contribute to the progressive disturbance in cerebral function. "Six missense mutations of gephyrin—V43L, A91T, G375D, G578A, G578S, and D697N—have previously been linked to ASDs and/or epileptic encephalopathy." (PMID 33532714, 2021). "We identified a de novo missense mutation (G375D) in the gephyrin gene (GPHN) in a patient with epileptic encephalopathy resembling Dravet syndrome." (PMID 26613940, 2015). "An impaired formation of higher oligomers, as seen in the pathogenic G375D‐gephyrin variant, hampers clustering at GABAergic synapses and leads to epileptic encephalopathy, highlighting the importance of the formation of higher oligomers for synaptic gephyrin clustering." (PMID 40781785, 2025). "For example, the collybistin mutation p.G55A associated with early infantile epileptic encephalopathy and severe psychomotor retardation has a clear dominant-negative effect, causing gephyrin aggregation in neurons and subsequent loss of synaptic gephyrin and GABAA receptor clusters." (PMID 30914922, 2019).
depression (3 papers, 2019 to 2025). "The same group using a bred-based model of depression, associated with memory dysfunction detected a reduction in the density of VGAT positive presynaptic but not of gephyrin positive postsynaptic terminals in hippocampal synapses of 11-12-week-old „helpless”mice." (PMID 30645585, 2019).
Dravet syndrome (3 papers, 2015 to 2021). "The functional relevance of our findings is supported by a recent study focusing on the involvement of gephyrin in a case of Dravet syndrome." (PMID 29464196, 2018). "Genetic screenings of GPHN in follow‐up cohorts of patients with different types of EEs, including Dravet syndrome, did not lead to the identification of additional mutations." (PMID 26613940, 2015).
glioma (3 papers, 2023 to 2025). A benign or malignant brain and spinal cord tumor that arises from glial cells (astrocytes, oligodendrocytes, ependymal cells). "Quantifying synaptic, colocalized gephyrin puncta and non-colocalized, extrasynaptic gephyrin puncta on DMG glioma cells following confocal microscopy and 3D reconstruction, we found that approximately 20% of glioma cell gephyrin puncta are colocalized with presynaptic VGAT." (PMID 39972132, 2025).
status epilepticus (3 papers, 2019 to 2025). Status epilepticus is defined as a continuous seizure lasting more than 30 min, or two or more seizures without full recovery of consciousness between any of them. "Accordingly, γ2 subunit and gephyrin levels both decrease in responses to other stimuli including status epilepticus or prolonged inhibition of IP3 receptor-dependent signaling." (PMID 31080408, 2019).
amyloidosis (2 papers, 2019 to 2023). A disorder characterized by the localized or diffuse accumulation of amyloid protein in various anatomic sites. "To address whether apical and basal dendrite differences in the E/I ratio occur in other brain regions, we compared PSD95 and gephyrin puncta in the hippocampal CA1 region, which displays dendritic hyperactivity in amyloidosis." (PMID 36640331, 2023). "We observed a small but not significant increase in PSD95 puncta and no change in gephyrin puncta in hAPP mice compared with the WT, consistent with our imaging data and other studies that show no change or increased excitatory synapse densities in early stages of amyloidosis." (PMID 36640331, 2023).
bipolar disorder (2 papers, 2017 to 2025). A disorder of the brain that causes unusual shifts in mood, energy, activity levels and the ability to carry out day-to-day tasks. "Previous studies have reported that GABRB1 is associated with bipolar disorder, and our data also revealed the notable increases of the inhibitory postsynaptic scaffolding protein Gephyrin and inhibitory receptor of GABRB1 in the Kif15-/- mice." (PMID 40892874, 2025).
cocaine addicts (2 papers, 2012 to 2013). "In contrast, GABRG2 was significantly down-regulated in alcoholics and cocaine addicts relative to controls and likewise GPHN was down-regulated in cocaine addicts." (PMID 22253714, 2012).
colon cancer (2 papers, 2011 to 2025). "Indeed, our genome-wide target profiling of piggyBac in HEK 293 revealed a piggyBac hotspot located within the coding region of gephyrin, a scaffold protein implicated in colon cancer and adult T-cell leukemia." (PMID 21447194, 2011). "GPHN is associated with chromosomal instability in colon cancer, but no lung cancer-related studies exist." (PMID 40297587, 2025).
ischemia (2 papers, 2019 to 2022). A hypoperfusion of the BLOOD through an organ or tissue caused by a PATHOLOGIC CONSTRICTION or obstruction of its BLOOD VESSELS, or an absence of BLOOD CIRCULATION. "Finally, we uncover that ischemia in hippocampal slices induces loss of gephyrin clusters and GABAergic synaptic transmission." (PMID 35307349, 2022). "SUMOylation-defective gephyrin K148R/K724R mutant transgene expression reversed these ischemia-induced changes in gephyrin cluster density." (PMID 35307349, 2022). "Calpain-1 mediated gephyrin cleavage can occur within 1 min in hippocampal membranes, and cleavage products are increased following in vitro ischemia at 30 min and up to 48 h following ischemic events in vivo." (PMID 31080408, 2019). "We speculated that during ischemia, increased BDNF expression could reduce synaptic abundance of GABAARs via PIAS-3–mediated gephyrin modification at K148 and K724 residues." (PMID 35307349, 2022). "Finally, using oxygen–glucose deprivation as an in vitro model for ischemia, we show that BDNF–tropomyosin-related kinase B signaling negatively impairs clustering of the main scaffolding protein at GABAergic postsynapse, gephyrin, whereby reducing GABAergic neurotransmission postischemia." (PMID 35307349, 2022).
startle disease (2 papers, 2018 to 2023). "Startle disease is caused by mutated GlyRs or other proteins expressed at inhibitory synapses such as the pre-synaptic GlyT2, the post-synaptic scaffold proteins gephyrin or collybistin." (PMID 30186111, 2018). "Gephyrin knock-out mice display a phenotype resembling startle disease and result in reduced synaptic clustering of GlyRs." (PMID 30186111, 2018).
anxiety disorder (1 paper, 2024). A category of psychiatric disorders which are characterized by anxious feelings or fear often accompanied by physical symptoms associated with anxiety. "However, there are three cysteine residues in the functional C‐terminal of gephyrin, Cys212, Cys284 and Cys293, we could not excluded the role of S‐nitrosylation at Cys293 of gephyrin in anxiety disorders." (PMID 38965798, 2024).
colorectal cancer (1 paper, 2025). A primary or metastatic malignant neoplasm that affects the colon or rectum. "In colorectal cancer, NCOA4 has been identified as the most prevalent partner, accounting for 63% of cases, followed by CCDC6, which accounts for 21% of cases, and GPHN (Gephyrin), accounting for 5% of cases." (PMID 41373459, 2025).
developmental delay (1 paper, 2014). "The second family has a 319 kb paternally inherited deletion in gephyrin and exhibits mild global developmental delay in early life, social difficulties, and repetitive behaviors." (PMID 25309321, 2014). "The third family has a 273 kb de novo deletion in gephyrin gene and exhibits developmental delay, cyclical seizures, and behavioral issues including anxiety, obsessive compulsive disorders, tics, and impulsive behaviors." (PMID 25309321, 2014).
diabetes (1 paper, 2018). "MiR-375 has been reported to inhibit diabetes by targeting the expression of mRNA targets of miR-375 such as Gephyrin (GPHN), Insulin induced gene 2 (INSIG2), Myotrophin (MTPN) and Eukaryotic translation elongation factor 1 (Eef1e1)." (PMID 30379973, 2018).
even-plus syndrome (1 paper, 2025). "For example, MAN2C1 is associated with congenital disorder of deglycosylation 2 (MIM #619775), GPHN with molybdenum cofactor deficiency C (MIM #615501), LRP2 with Donnai–Barrow syndrome (MIM #222448), and HSPA9 with Even-plus syndrome (MIM #616854)." (PMID 40282865, 2025).
glaucoma (1 paper, 2025). Increased pressure in the eyeball due to obstruction of the outflow of aqueous humor. "Only one study reported GPHN expression changing in the context of an autoimmune model of glaucoma, which is the opposite of what we found in our study." (PMID 40076480, 2025).
Hyperammonemia (1 paper, 2022). An increased concentration of ammonia in the blood. "Hyperammonemia increased the content of gephyrin and the phosphorylation of the β3 subunit of GABAA receptor in the cerebellum; these increases were reversed by blocking TrkB with ANA12, TNFR1 with R7050, S1PR2 with JTE-013, or CCR2 with RS504393." (PMID 36233065, 2022). "The reported results also suggest that the increased membrane expression of GABAA receptors in hyperammonemia is mediated by the BDNF–TrkB-induced increase in gephyrin and in the phosphorylation of the β3 subunit of GABAA receptors." (PMID 36233065, 2022).
idiopathic generalized epilepsy (1 paper, 2015). A generalised epilepsy that encompasses several common seizure phenotypes including childhood absence epilepsy, juvenile absence epilepsy, juvenile myoclonic epilepsy and epilepsy with generalized tonic-clonic seizures alone. "More recently, we and others have identified large deletions in GPHN in patients with different neurological disorders such as idiopathic generalized epilepsy (IGE), autism, schizophrenia and seizures." (PMID 26613940, 2015).
Intellectual disability (1 paper, 2019). "Taken together, our analysis strongly suggests that the collybistin p.R356Q variant is responsible for the mild intellectual disability observed in this family—due to disruption of collybistin PI3P binding, leading to a decrease in synaptic gephyrin and GABAA receptor clustering." (PMID 30914922, 2019).
mediastinal cancer (1 paper, 2015). "Gephyrin is a protein involved in clustering both GlyR and GABAaR and antibodies to this protein were described in a single patient with SPS and mediastinal cancer." (PMID 25774787, 2015).
retinal degeneration (1 paper, 2021). Degeneration of the retina. "Recently, a significantly lower inhibitory post-synapse signal was visualized by anti-gephyrin in a later stage of retinal degeneration." (PMID 35053014, 2021).
Stroke (1 paper, 2022). Sudden impairment of blood flow to a part of the brain due to occlusion or rupture of an artery to the brain. "Indeed, our group recently demonstrated that gephyrin affects microglial reactivity and synapse stability after stroke." (PMID 36314779, 2022).
tauopathy (1 paper, 2020). Neurodegenerative disorders involving deposition of abnormal tau protein isoforms (tau proteins) in neurons and glial cells in the brain. "Previous reports from tauopathy mouse models revealed selectivity for C1q interaction with PSD95 and not gephyrin." (PMID 31906973, 2020).
temporal lobe epilepsy (1 paper, 2015). A localization-related (focal) form of epilepsy characterized by recurrent seizures that arise from foci within the temporal lobe, most commonly from its mesial aspect. "Previously, we have identified stress‐induced irregular splicing of GPHN resulting in the expression of truncated gephyrin variants in patients with temporal lobe epilepsy." (PMID 26613940, 2015).
X-linked intellectual disability (1 paper, 2019). An X-linked intellectual deficiency in which not enough information is known, reported or published to indicate whether a gene causes non-syndromic or syndromic presentations. "This process is disrupted by mutations in the collybistin gene (ARHGEF9), which cause X-linked intellectual disability (XLID) by a variety of mechanisms converging on disrupted gephyrin and GABAA receptor clustering at central synapses." (PMID 30914922, 2019).
neurological diseases (7 papers, 2014 to 2025). "Dysfunctions related to gephyrin-mediated neurotransmission have been implicated in several neurological disorders, such as neurodevelopmental disorders, epilepsy, and even neurodegenerative diseases like Alzheimer’s." (PMID 40868159, 2025). "Gephyrin mutations have been linked to various neurological disorders; however, systematic analyses of the functional consequences of these mutations are lacking." (PMID 33532714, 2021). "Given that aberrant protein palmitoylation is implicated in a range of neurological diseases, it will be interesting to see whether deregulated gephyrin palmitoylation contributes to pathogenesis in these disorders." (PMID 25025157, 2014). "Overall, we show that alternative splicing of GPHN is an important genetic variation to consider in neurological diseases and a determinant of the diversity of postsynaptic inhibitory synapses." (PMID 35717442, 2022). "Overall, our study shows that a detailed appreciation of the GPHN splice variant landscape is required to evaluate aberrant expression of GPHN isoforms in neurological diseases." (PMID 35717442, 2022). "Among the GPHN transcriptome, we sought transcripts containing exon-exon junctions mimicking the genetic variations of GPHN previously characterized in patients with neurological disorders." (PMID 35717442, 2022). "Thus, these molecules could serve as potent gephyrin-specific modulators with therapeutic benefits in several neurological disorders." (PMID 40868159, 2025).
cancer (6 papers, 2011 to 2023). A tumor composed of atypical neoplastic, often pleomorphic cells that invade other tissues. "Notably, piggyBac targeted twice to the same site within one particular cancer-related gene, gephyrin (GPHN), raising a great concern for its safe use in gene therapy." (PMID 21447194, 2011). "The remaining four have no known cancer‐related function (KIAA1109, GPHN, GPR25, ZNF462)." (PMID 30809968, 2019).
neurodevelopmental disorder (4 papers, 2012 to 2021). A behavioral and cognitive disorder with onset during the developmental period that involves impaired or aberrant development of intellectual, motor, or social functions. "Gephyrin has functional links with several synaptic proteins, mutations of which have been reported in various neurodevelopmental disorders." (PMID 34621295, 2021). "Dysfunctions in receptor-mediated or gephyrin-mediated neurotransmission have been identified in various severe neurodevelopmental disorders." (PMID 30258351, 2018).